NEXN (nexilin F-actin binding protein)
Diseases named in the same sentence as NEXN in open-access papers:
NEXN is named in the same sentence as 53 diseases in open-access papers, as found by Europe PMC text mining. Sharing a sentence is not in itself a finding about the gene and the disease. The quoted sentences say what the papers report.
cardiomyopathy (15 papers, 2013 to 2025). A disease of the heart muscle or myocardium proper. "Global knockout of NEXN in mice has been reported to cause a rapidly progressive cardiomyopathy leading to lethality shortly after birth." (PMID 39982482, 2025). "Homozygous deletion of the NEXN G650 residue causes cardiomyopathy in mice, while adeno-associated virus–mediated NEXN gene delivery can restore cardiomyocyte function." (PMID 40440261, 2025). "From a genetic testing standpoint, the increasing use of whole exome/genome sequencing in acutely unwell infants presenting with cardiomyopathy will help define the full spectrum of clinical severity associated with biallelic NEXN variants." (PMID 41347213, 2025). "Nexilin is a component of the junctional membrane complex that required for the development and maintenance of cardiac T-tubules, and multiple mutations of NEXN has been identified to associate with cardiomyopathy." (PMID 38783323, 2024). "Multiple mutations in NEXN have been associated with cardiomyopathies, highlighting the importance of this protein for cardiac function." (PMID 35907876, 2022). "Variants in NEXN have been associated with cardiomyopathies, highlighting its importance for cardiac function." (PMID 32814711, 2020). "Recently, several variants in the nexilin (NEXN) gene have been associated with cardiomyopathy." (PMID 32814711, 2020). "The role of NEXN in heart has been well established in Z-disc stabilization and force generation, and mutant NEXN in patients leads to cardiomyopathies." (PMID 24349201, 2013). "Moreover, an evaluation of NEXN variants in patients with cardiomyopathy or sudden cardiac death showed a predominance of DCM, with particularly severe and early-onset phenotypes in those with double NEXN variants." (PMID 39337275, 2024). "Whether NEXN-dependent cardiomyopathy is defined by dilation or hypertrophy depends on the localization of the NEXN mutation." (PMID 30158653, 2018). "Constitutive knockout models in mice demonstrated that the absence of NEXN leads to rapid progression of cardiomyopathy, characterized by left ventricular dilation, thinning of the ventricular walls, and a decline in cardiac function." (PMID 39337275, 2024).
dilated cardiomyopathy (12 papers, 2014 to 2025). Cardiomyopathy which is characterized by dilation and contractile dysfunction of the left and right ventricles. "Emerging genetic evidence has identified NEXN as a high-confidence gene associated with dilated cardiomyopathy (DCM), supporting its routine inclusion in the genetic evaluation of the condition." (PMID 40440261, 2025). "Nexilin (NEXN) has been identified as a high-confidence gene associated with dilated cardiomyopathy." (PMID 40440261, 2025). "In humans, NEXN variants have previously been shown to be associated with dilated cardiomyopathy (DCM), predominantly in adults with average age of onset above 50 years in the context of heterozygous variants." (PMID 41347213, 2025). "Nexilin (NEXN) plays a crucial role in stabilizing the sarcomeric Z-disk of striated muscle fibers and, when mutated, leads to dilated cardiomyopathy in humans." (PMID 38114601, 2023). "Several loss-of-function mutations in NEXN have been identified in both dilated cardiomyopathy and hypertrophic cardiomyopathy." (PMID 36465446, 2022). "We identified genes that have previously been implicated in heart development and structural heart malformations (e.g. MBNL1, ROR1), and known disease-related genes (e.g. NEXN, dilated cardiomyopathy; NDUFS1, mitochondrial complex I deficiency)." (PMID 31314787, 2019). "Thus, mRNA overexpression in zebrafish was used for example to analyze mutations in the NEXN (Nexilin) gene that were identified in human DCM (dilated cardiomyopathy) patients." (PMID 29911105, 2018). "NEXN is a Z-disk gene which is associated with dilated cardiomyopathy." (PMID 25628539, 2014). "The most frequently mutated genes related to dilated cardiomyopathy (DCM) were TTN, MYH7, NEXN, TNNI3, and SCN5A." (PMID 41341110, 2025). "This lncRNA is transcribed in an antisense manner with respect to its target gene, NEXN (nexilin F-Actin binding protein), which is important in cardiac T-tubule formation: cardiac loss of NEXN in mice resulted in a rapid progression to dilated cardiomyopathy." (PMID 36768528, 2023). "For example, mutations in JUP, DSP, PKP2, DSG2, DSC2, CTNNA3, CDH2, or PLN (all of them more abundant in LV) predominantly lead to arrhythmogenic right ventricular cardiomyopathy, and mutations in MYH7, HSPB7, NEXN and MYPN (also all more abundant in LV) lead to dilated cardiomyopathy." (PMID 32291283, 2020).
atherosclerosis (6 papers, 2020 to 2023). A disease characterized by the build-up of fatty material and calcium deposition in the arterial wall resulting in partial or complete occlusion of the arterial lumen. "NEXN deficiency results in enhanced atherosclerosis, whereas NEXN overexpression reduces atherosclerosis in mice model of atherosclerosis." (PMID 33340430, 2021). "NEXN deficiency promoted atherosclerosis and plaque inflammation in WD-fed ApoE−/− mice, while NEXN overexpression prevented these effects." (PMID 32772181, 2020). "NEXN+/−ApoE−/−mice (NEXN−/−ApoE−/− mice were embryonically lethal) had substantially increased atherosclerotic burden and thinner cap fibroatheroma than ApoE−/−mice, indicating that NEXN plays a protective role against the development of vulnerable atherosclerotic plaques and atherosclerosis." (PMID 32241300, 2020). "Up-regulated DEGs included known atherosclerosis genes such as the liver X receptor gene NR1H2, and NEXN, TRAF1, TLR7 and LGALS3BP, implicating tumor necrosis factor and toll-like receptor signaling and glycan-binding protein pathways." (PMID 37205656, 2023).
cardiac hypertrophy (4 papers, 2022 to 2025). "These included a variant in the promoter region of NEXN, c.-194A>G, which was significantly associated with decreased expression of NEXN and cardiac hypertrophy." (PMID 37830612, 2023). "CLK4 interacts and phosphorylates NEXN at serine 437, and reduced NEXN phosphorylation is associated with cardiac hypertrophy and dysfunction." (PMID 35907876, 2022). "In a cohort of nine SADS and four SUDI (sudden unexplained death in infancy) cases, they identified a rare variant in the promoter region of NEXN (c.-194 A > G), that was statistically significantly associated with reduced NEXN expression and cardiac hypertrophy." (PMID 39982482, 2025). "We conclude that CLK4 regulates cardiac function through phosphorylation of NEXN, and its deficiency may lead to pathological cardiac hypertrophy." (PMID 35907876, 2022). "Thus, the mechanism by which cardiomyocyte-specific loss-of Clk4 leads to cardiac hypertrophy and heart failure might involve a decrease in NEXN phosphorylation." (PMID 35907876, 2022). "Here the authors show that the kinase CLK4 ameliorates cardiac hypertrophy by phosphorylating NEXN." (PMID 35907876, 2022). "Importantly, restoring phosphorylation of NEXN ameliorates myocardial hypertrophy in mice with cardiac-specific Clk4 deletion." (PMID 35907876, 2022). "Herein, we reveal that CLK4 acts as a key regulator of pathological cardiac hypertrophy and that its direct substrate NEXN might have a critical role in the process." (PMID 35907876, 2022). "Mechanistically, we identified nexilin (NEXN) as the direct target of CLK4 and the reduction of phosphorylated NEXN mediated the development of pathological myocardial hypertrophy and heart failure in Clk4-cKO mice." (PMID 35907876, 2022).
hypertrophic cardiomyopathy (4 papers, 2022 to 2025). "In humans, heterozygous NEXN mutations have been reported to cause dilated or hypertrophic cardiomyopathy with incomplete penetrance and variable age of onset." (PMID 39982482, 2025). "NEXN (encode Nexilin) is related to cardiovascular diseases, including hypertrophic cardiomyopathy, coronary artery disease, and septal defects." (PMID 35096061, 2022).
atrial septal defect (3 papers, 2022 to 2025). Interauricular communication is a congenital malformation characterized by a communication between the atrial chambers of the heart. "Genetic evaluation and testing revealed that the patient harbored a novel truncated variant G100X in NEXN, which is an F-actin binding protein at cell–matrix junctions and is implicated in atrial septal defect (ASD) and cardiomyopathies." (PMID 36465446, 2022). "Although NEXN variants have not previously been described in cases of complex congenital heart disease, such as TGA, gain-of-function NEXN variants resulting in GATA4 suppression have been described as the cause of secundum atrial septal defects in both mouse models and humans." (PMID 41347213, 2025). "It has also been shown that in transgenic mice transgenic mice with cardiac-selective overexpression of NEXN developed an atrial septal defect (ASD) phenotype and that NEXN mutations in ASD patients inhibit GATA4." (PMID 39000221, 2024). "Although gain-of-function NEXN variants have been implicated in the pathogenesis of atrial septal defects in mice and humans, no cases of complex congenital heart disease have been described in loss-of-function NEXN variants comparable to this case." (PMID 41347213, 2025).
coronary artery disease (3 papers, 2013 to 2025). "Notably, genetic findings have identified a variant of NEXN associated with the susceptibility to coronary artery disease." (PMID 40440261, 2025). "Additionally, the association between NEXN and human coronary artery disease has been previously reported." (PMID 40440261, 2025). "In summary, our study demonstrated NEXN is a novel susceptibility gene for CAD, which provides evidence on the contribution of the F-actin regulator for VSMC phenotypic modulation and for coronary artery diseases." (PMID 24349201, 2013). "However, it is unknown whether or not NEXN is associated with susceptibility of coronary artery disease." (PMID 24349201, 2013).
diabetes (3 papers, 2013 to 2025). "Secondly, gender, age, obesity, diabetes, hyperlipidemia and smoking do not significantly increase its susceptibility to CAD, suggesting NEXN acting as an independent factor to the pathogenesis of CAD." (PMID 24349201, 2013).
heart failure (3 papers, 2021 to 2024). Inability of the heart to pump blood at an adequate rate to meet tissue metabolic requirements. "Taken together, these findings indicate that Clk4 deficiency-mediated heart failure may be caused primarily by decreased NEXN phosphorylation." (PMID 35907876, 2022).
Obesity (3 papers, 2013 to 2024). Accumulation of substantial excess body fat. "Among these genes, AHI1, AKAP9, ANKRD12, CCDC18, IFT74, NEXN, etc., have been shown to play an important role in adipose deposition or obesity." (PMID 38474122, 2024). "Reports have already shown that ANKRD12, NEXN, IFT74, and ROCK1 play an important role in adipose deposition or obesity." (PMID 38474122, 2024).
glaucoma (2 papers, 2025). Increased pressure in the eyeball due to obstruction of the outflow of aqueous humor. "ETNK1, VMAC, NEXN, and SUN1 were identified as glaucoma-associated autoantibodies based on their plasma levels and positive rates." (PMID 41463042, 2025). "In all glaucoma types, the four glaucoma-associated autoantibodies other than NEXN did not correlate significantly with any of the clinical factors: MD, IOP, IOL AL, CCT, or age." (PMID 40149693, 2025). "In this study, a cohort of cataract, NTG, and POAG patients was examined by CWPA for plasma autoantibodies, and four new autoantibodies, ETNK1, VMAC, NEXN, and SUN1, were detected as glaucoma-related." (PMID 40149693, 2025). "If NEXN is released from trabecular cells or RGCs by elevated IOP in an early stage of OAG, NEXN may contribute to the pathogenesis of glaucoma in a previously uncharacterized manner." (PMID 40149693, 2025).
Hypertension (2 papers, 2013 to 2021). The presence of chronic increased pressure in the systemic arterial system. "It is tempting to speculate that NEXN regulates VSMC function to participate in both hypertension and CAD." (PMID 24349201, 2013).
Arrhythmia (1 paper, 2022). Any cardiac rhythm other than the normal sinus rhythm. "Most of these variants were located in genes associated with inherited arrhythmias and arrhythmic cardiomyopathies, such as MYBPC3, KCNQ1, TTN, CASQ2, GPD1L, DPP6, HCN4 and NEXN." (PMID 36008935, 2022).
arterial disorder (1 paper, 2025). An impairment of the structure or function of the blood vessels which carry blood away from the heart. "This study reveals an important causal role of NEXN in the uncontrolled proliferation of VSMCs and subsequent arterial disorders, suggesting NEXN as a potential therapeutic target for proliferative arterial diseases." (PMID 40440261, 2025).
congenital heart disease (1 paper, 2025). A heart disease that is present at birth. "If additional reports of congenital heart disease in association with biallelic NEXN variants emerge with time, then further investigations into the potential mechanisms would be justified." (PMID 41347213, 2025). "We have described the first case of complex congenital heart disease in the context of a patient with a homozygous NEXN variant and early-onset DCM." (PMID 41347213, 2025). "It is feasible that the different, biallelic loss-of-function NEXN variant seen in this patient may be associated with other forms of congenital heart disease." (PMID 41347213, 2025). "NEXN variants have previously been described as a cause of both pediatric- and adult-onset dilated cardiomyopathy but are not known to be associated with complex congenital heart disease." (PMID 41347213, 2025).
gastric cancer (1 paper, 2021). A primary or metastatic malignant neoplasm involving the stomach. "Herein, we observe that has-miR-590-3p could promote the progression of melanoma by inhibiting NEXN. has-miR-374b-5p can suppress bladder 42, ovarian 43, and pancreatic cancers 44, while it can promote gastric cancer cell invasion and metastasis." (PMID 33758620, 2021).
melanoma (1 paper, 2021). A malignant, usually aggressive tumor composed of atypical, neoplastic melanocytes. "NEXN can control actin polymerization in smooth muscle 38, and its implication on melanoma has not been reported." (PMID 33758620, 2021).
multiple sclerosis (1 paper, 2022). A progressive autoimmune disorder affecting the central nervous system resulting in demyelination. "NEXN was detected as a novel IFN-β response gene in multiple sclerosis." (PMID 35778531, 2022).
osteosarcoma (1 paper, 2022). A usually aggressive malignant bone-forming mesenchymal neoplasm, predominantly affecting adolescents and young adults. "Four key genes (LTF, C10orf107, HIST1H2AK, and NEXN) were identified to be correlated with the prognosis of osteosarcoma patients." (PMID 35096061, 2022). "Four key genes (C10orf107, HIST1H2AK, NEXN, and LTF) were found to be correlated with the prognosis of osteosarcoma patients." (PMID 35096061, 2022). "The expression of C10orf107 and NEXN was positively correlated with poor survival of osteosarcoma patients, whereas the expression of HIST1H2AK and LTF was negatively correlated with poor survival of osteosarcoma patients." (PMID 35096061, 2022).
rectal cancer (1 paper, 2025). A primary or metastatic malignant neoplasm that affects the rectum. "In this study, we identified four molecular markers (MYLK, FLNC, MYH11, and NEXN) as potential prognostic biomarkers for rectal cancer for the first time." (PMID 39762799, 2025).
cancer (3 papers, 2013 to 2017). A tumor composed of atypical neoplastic, often pleomorphic cells that invade other tissues. "Finally, NEXN was reported to be involved in cell motility and adhesion of HeLa cancer cells through the binding link from actin and the plasma membrane." (PMID 24504141, 2014). "Additionally, aspirin treatment also significantly decreased the expression of genes encoding cytoskeleton including ARPC5, NEXN and LRPPRC, which may be helpful to understand the mechanisms behind aspirin suppressing the metastasis of cancer cells." (PMID 28184026, 2017). "The roles of the NEXN gene in cancer have not yet been investigated." (PMID 23940558, 2013).
cardiovascular disease (2 papers, 2014 to 2022). "NEXN was the top down-regulated gene in antidepressant-treated women and also turned out to be involved in cardiovascular disease, skeletal and muscular disorders, cardiovascular system development and function pathway in antidepressant-treated women." (PMID 25628539, 2014).
heart disease (1 paper, 2018). "If NEXN is similarly responsive to glucocorticoids in cardiomyocytes remains to be established, but this could have therapeutic implications in heart disease caused by partial loss-of-function mutations in NEXN." (PMID 30158653, 2018).
vascular disorder (1 paper, 2013). A general term used to describe any disease affecting blood vessels]. "Whether NEXN contributes to human vascular disorders is still unknown." (PMID 24349201, 2013).
NEXN also shares sentences with these, for which no sentence is quoted: tumor (3 papers); African trypanosomiasis (1); Alstrom syndrome (1); Aortic dissection (1); arrhythmogenic right ventricular cardiomyopathy (1); breast carcinoma (1); carnitine deficiency (1); channelopathy of (1); chordoma (1); familial dilated cardiomyopathy (1); hereditary hemorrhagic telangiectasia (1); hyperlipidemia (1); hypertrophy (1); ichthyosiform erythroderma (1); intrinsic cardiomyopathy (1); long QT syndrome (1); Marfan syndrome (1); mucopolysaccharidosis (1); muscular disorders (1); myocardial infarction (1); Nicotine addiction (1); Noonan syndrome (1); open-angle glaucoma (1); pancreatic cancers (1); Patent ductus arteriosus (1); Right ventricular cardiomyopathy (1); type 2 diabetes mellitus (1); Varicose veins (1); Williams syndrome (1).